KL (klotho)
Diseases named in the same sentence as KL in open-access papers (continued):
Sharing a sentence is not in itself a finding about the gene and the disease.
lung carcinoma (35 papers, 2010 to 2025). "This study aimed to identify the co-expression protein networks and proteomic profiles associated with A549/KL cells to understand how Klotho protein expression affects molecular networks associated with lung carcinoma malignancy." (PMID 38267588, 2024). "We performed a screen for tumour‐secreted cytokines and chemokines using mice carrying inducible KrasG12D/+ and Stk11/Lkb1flox/flox (KL) alleles, a well‐established genetically engineered mouse model that develops aggressive lung cancer." (PMID 37759102, 2023). "To assess the clinical relevance of this finding, we compared the KL tumor DEGs to a list of 345 human lung cancer DEGs associated with poor prognosis from the TCGA52." (PMID 35941104, 2022). "This study investigated the role and underlying mechanism of m6A modulation in aggressive KL mutant lung cancer cells." (PMID 34016959, 2021). "LKB1 inactivation causes DNA hypermethylation and histone methylation, which facilitates immune escape in KL-mutated lung cancer and represses anti-oncogenic STING32." (PMID 34016959, 2021). "Oncogenic KRAS mutations combined with the loss of the LKB1 tumor-suppressor gene (KL) are strongly associated with aggressive forms of lung cancer." (PMID 34016959, 2021). "In addition, clinical studies have suggested that lung cancer patients with KL mutations are resistant to most cancer therapies, indicating increased aggressiveness compared to patients with KP mutations." (PMID 38997257, 2024). "This study aimed to identify co-expression protein networks associated with A549/KL cells, compared with those of A549 cells, to understand how Klotho protein expression affects molecular networks associated with the malignant nature of lung carcinoma cells." (PMID 38267588, 2024). "To elucidate the chief culprit leading to impaired trafficking and adhesion of T cells in LKB1 deficient lung cancer, we exploited inch-by-inch search among different cell types and compared their differential biological functions between KL and K samples using scRNA-seq data." (PMID 36871040, 2023). "Interestingly, there are investigations demonstrating Klotho deficiency as a biomarker for kidney injury and for number of cancers, including breast cancer, lung cancer or hepatocellular carcinoma." (PMID 32319182, 2020). "In summary, our results demonstrate that the klotho, an anti-aging gene, is associated with the resistance of lung cancer cells to cisplatin and may alleviate the resistance mainly through modulating the PI3K/Akt signal pathway and the expression of bax/bcl-2." (PMID 23437382, 2013). "Several studies have identified that methylation of klotho gene is a major cause of its down-regulation in cervical cancinoma,breast cancer and colorectal cancer, and whether this is true in lung cancer cells remains to be investigated in future studies." (PMID 23437382, 2013). "The transfection of Klotho into SQ5 lung cancer cells revealed that Klotho inhibited the mesenchymal marker N-cadherin, although it had no impact on other EMT markers like Snail, vimentin, or the epithelial marker E-cadherin." (PMID 40004457, 2025). "Klotho acts as an anti-oncogene in human lung cancer cell line A549 by inhibiting cell growth and promoting apoptosis." (PMID 39796185, 2025). "Although our GEMM findings highlight the role of G6PD in promoting KL, not KP, tumorigenesis, a deeper investigation is warranted to comprehend the implications of this discovery for the growth and treatment of KL or KP tumors in lung cancer patients." (PMID 38997257, 2024). "In addition, the distribution of mtdsRNA in mitochondria versus cytosol seemed to differ between lung cancer cell lines with KP and KL mutations, suggesting that NSCLC cells with loss-of-function mutations in the LKB1 (STK11) gene may have stronger activation of the IFN-1 pathway." (PMID 38955468, 2024).
lung carcinoma (continued). "Clinically, we sought to learn how the KL gene and protein affect malignancies, to develop treatment strategies to improve outcomes of patients with lung cancer." (PMID 38267588, 2024). "We previously identified and characterized a genetic mouse model of lung cancer (KL: KrasLSL-G12D/+;Lkb1flox/flox) that accurately reproduces CACS20." (PMID 35941104, 2022). "Knockout of PPDPF expression in the KL mouse model of lung cancer inhibited tumorigenesis de novo, improving the survival of the mice." (PMID 34975328, 2022). "SHANK1 bound with KL and MDM2, and downregulated KL by ubiquitin degradation, and it promoted the migration, invasion, and proliferation abilities of lung cancer cells." (PMID 35468874, 2022). "In lung cancer, drug-resistant tumor cells express significantly less Klotho than drug-sensitive lines and show greater autophagy, reflected in upregulation of Beclin1 and LC3-II." (PMID 34737707, 2021). "KL inhibits lung cancer cell proliferation, growth, invasiveness, and migration and fosters apoptosis, effects, at least in part, dependent on IGF-1R/AKT and Wnt3a/β-catenin signaling and on reduced interleukin 6 (IL-6) and IL-8 production." (PMID 33520985, 2020). "KL is down-regulated in lung cancer cells and tissues and even more so in chemotherapy-resistant lung cancer." (PMID 33520985, 2020). "MiR-10b lowers, Ras-related GTPase Ras8 up-regulates KL expression in non–small-cell lung cancer cells." (PMID 33520985, 2020). "Our previous study also found this phenomenon in human lung cancer cells (A549 cells) in which klotho also conferred a pro-apoptotic effect through the bax/bcl-2 pathway." (PMID 23437382, 2013). "The resistance of the lung cancer cells to chemotherapeutics is related to the low klotho expression." (PMID 23437382, 2013). "Emerging evidence demonstrates that klotho has a close relationship with cancers, including lung cancer, breast cancer, etc, by inhibiting the proliferation and promoting apoptosis of cancer cells." (PMID 23437382, 2013). "In our previous study, results demonstrated that the new anti-aging gene klotho was crucial for the proliferation and apoptosis of lung cancer cells (A549 cells), mainly through inhibiting the IGF-1/R pathway." (PMID 23437382, 2013). "Overexpression of klotho reduced the proliferation of lung cancer A549 cells, whereas klotho silencing in A549 cells enhanced proliferation." (PMID 20642846, 2010). "In this study, we detected changes in biological behavior after overexpression or knockdown of klotho in lung cancer cell line A549, and found that it also acts as a potential tumor suppressor in lung cancer." (PMID 20642846, 2010). "We found that the expression of klotho in lung cancer cell line A549 is low, and klotho overexpression inhibits, whereas klotho downregulation enhances, lung cancer cell growth." (PMID 20642846, 2010). "We studied the effect of klotho on IGF-1 pathway activation in A549 lung cancer cells, which express high levels of IGF-1R and show an enhanced proliferation following IGF-1 treatment." (PMID 20642846, 2010). "Additionally, we evaluated the performance of the pipeline on murine lung cancer cell lines KP (KrasG12DTp53−/−) (n = 5) and KL (KrasG12DLkb1−/−) (n = 5)." (PMID 40038430, 2025). "The KRAS driven lung cancers can be categorized into different subsets (such as KL, KP, KC, etc)." (PMID 34918209, 2021). "KL may sensitize lung cancer cells to apoptosis induction by cisplatin via PI3K/AKT signaling or due to decreased autophagy." (PMID 33520985, 2020). "Furthermore, they also showed that Klotho administration suppressed the metastases of lung cancer xenograft models." (PMID 32585905, 2020). "In lung cancer cells, Klotho, as a novel secreted Wnt antagonist, could inhibit activation of Wnt /beta-catenin signaling pathway, in a dose-dependent manner." (PMID 26499380, 2015).
lung carcinoma (continued). "Based on the in vitro experiment of klotho in the cisplatin resistance of lung cancers, we further examined if klotho expression affects the cispaltin sensitivity in vivo, A549DDP-lenti-sh-2 and A549DDP-lenti-scramble cells were injected subcutaneously into the right flank of nude mice." (PMID 23437382, 2013). "Klotho could also inhibit proliferation and increase apoptosis of human lung cancer A549 cells, which may be partly due to the inhibition of IGF-1/insulin pathways and involving regulating the expression of the apoptosis-related genes bax/bcl-2." (PMID 23516476, 2013). "In contrast to previous studies indicating Klotho as a putative tumor suppressor gene in human breast cancer, kidney cancer and lung cancer, our present study reveals the oncogenic function of Klotho in hepatocarcinogenesis, which is consistent with previous findings in epithelial ovarian cancer." (PMID 23516476, 2013). "In our study, we for the first time demonstrated that klotho could attenuate the resistance of lung cancer to cisplatin based chemotherapy and the apoptosis of the resistant cells with klotho overexpression was markedly increased." (PMID 23437382, 2013). "In a recent report, KL promoted apoptosis and growth inhibition in lung cancer cells." (PMID 21483740, 2011). "In this study, we investigated the effects of klotho in lung cancer cells." (PMID 20642846, 2010). "Since secreted klotho protein can inhibit the activation of insulin/IGF-1 receptors, we presumed that klotho may also function as a suppressor of lung cancer." (PMID 20642846, 2010). "Further study of the biological functions of klotho may be helpful in developing new strategies in lung cancer treatment." (PMID 20642846, 2010). "Recent research indicated that α‐Klotho, designated as Klotho, was involved in the progression of a variety of human cancers as a tumor suppressor, including hepatocellular carcinoma, colorectal cancer, renal cell carcinoma, pancreatic cancer, breast cancer, and lung cancer and so on." (PMID 35841322, 2023). "The abnormal autophagy in tumors may be associated with Klotho underexpression, which has been documented in hepatocellular carcinoma, head and neck squamous cell carcinoma (HNSCC), gastric cancer, as well as lung cancer." (PMID 34737707, 2021). "Klotho may be a tumor suppressor in a wide range of malignancies that include breast cancer, cervical cancer, pancreatic cancer, melanoma, gastric cancer, colorectal cancer, lung cancer, liver cancer, renal cell carcinoma, and ovarian cancer." (PMID 29250031, 2017). "In summary, klotho, a potential tumor suppressor, can inhibit the growth of lung cancer cells A549 and promote their apoptosis, this may be partly due to the inhibition of IGF-1/insulin pathways and involving regulating the expression of the apoptosis-related genes bax/bcl-2." (PMID 20642846, 2010). "Klotho can inhibit the IGF-1/insulin and Wnt/β-catenin signaling pathways, promoting autophagy and apoptosis of lung cancer cells, thus exerting an inhibitory effect on tumor growth." (PMID 38287280, 2024). "Moreover, Klotho has also been shown to increase the efficacy of chemotherapy, including cisplatin in human lung cancer by modulating the phosphatidylinositol 3-kinase/protein kinase B PI3K/AKT pathway, indicating that Klotho therapy may be effective in combination with existing cancer therapies." (PMID 32585905, 2020). "For instance, like methylation of the KL promoter region, how epigenetic regulation of KLB expression in relation to FGF19/FGFR4 signaling during lung cancer progression remains an interesting question." (PMID 31695781, 2019). "Overall, SHANK1 expression was significant in its negative correlation with KL expression in lung cancer tissue." (PMID 35468874, 2022).
lung carcinoma (continued). "We and other research groups have found that KL is an anti-aging gene but has a lack of expression in lung cancer, and that it plays an important role in the development of lung cancer, drug resistance, etc.." (PMID 35468874, 2022). "Our data show that NANOG is expressed in KL mouse model and functionally important in maintaining lung cancer stemness; however, it is not significantly expressed in human lung ADC." (PMID 33439550, 2021). "In this study, we hypothesized klotho could inhibit the PI3K/Akt pathway and further to alleviate the resistance of lung cancer cells to cisplatin and may serve a potent candidate for the gene therapy of lung cancer." (PMID 23437382, 2013). "Importantly, the authors found that STING silencing was associated with LKB1 loss also in KRAS WT lung cancers, and was especially robust when combined with elevated DNMT1 levels, suggesting that this mechanism is not purely limited to the KL cellular state." (PMID 38791897, 2024). "Interestingly, the peptide ILDKKVE[KL] was detected in five of the lung cancer patients, exclusively in tumor tissues, and it was not identified in any benign tissue included in the HLA Ligand Atlas64." (PMID 38490980, 2024).
arteriosclerosis (34 papers, 2010 to 2025). A vascular disorder characterized by thickening and hardening of the walls of the arteries. "Although Klotho-deficient mice are viable with early aging like properties including arteriosclerosis and short life span, pigs carrying foetuses with a monoallelic knockout of the KL gene faced challenges in maintaining pregnancies to full term." (PMID 38486352, 2024). "On the contrary, mice homozygous for mutations in the klotho gene exhibit many pathways of the aging process including skin atrophy, shortened lifespan, growth retardation, arteriosclerosis, and osteoporosis." (PMID 36814582, 2023). "fortuitously discovered that Klotho-deficient mice developed several symptoms resembling human aging, including shortened lifespan, arteriosclerosis, and multiple organ degeneration." (PMID 35197934, 2022). "Defects in the klotho gene have been shown to result in arteriosclerosis and increased IMT in klotho deficient mice." (PMID 21241491, 2011). "Interestingly, Klotho was more strongly associated with AF than the presence of traditional cardiovascular risk factors such as complete loss of kidney function, age, gender, arteriosclerosis and valvular heart disease." (PMID 24991914, 2014). "The expression of klotho protein is beneficial to cardiovascular diseases by improving endothelial dysfunction and alleviating arteriosclerosis." (PMID 36814582, 2023). "Disruption of Klotho gene determines shortened life span due to premature arteriosclerosis in mice and AKI-induced Klotho deficiency accelerates renal fibrogenesis, retards renal tissue regeneration and promotes AKI-CKD transition." (PMID 35359949, 2022). "The actions of Klotho have been extensively studied in animals, starting from the discovery of the Klotho gene in mice in 1997; Klotho-depleted animals exhibited a wide array of symptoms mimicking ageing, one of which was premature arteriosclerosis." (PMID 31185930, 2019). "Klotho functions as a co-receptor for FGF-23, a key regulator of phosphate metabolism, and Klotho-deficient mice exhibit hallmarks of aging, including vascular calcification and arteriosclerosis." (PMID 40186651, 2025). "Klotho is involved in the prevention of arteriosclerosis, inducing its effects even in tissues that do not express it, which indicates its endocrine role." (PMID 34730891, 2021).
type 2 diabetes (34 papers, 2006 to 2025). "Here, we evaluate the association between s-Klotho levels, glycemic control and renal function in patients with type 2 diabetes (T2D)." (PMID 35286490, 2022). "In conclusion, in our cohort of people with type 2 diabetes, lower circulating levels of the vascular protective hormone Klotho are associated with increased risk of new onset and progression of diabetic eye disease." (PMID 33225726, 2020). "In people with type 2 diabetes, lower circulating levels of the vascular protective hormone Klotho are associated with increased risk of progression of diabetic retinopathy." (PMID 33225726, 2020). "Further, low S-Klotho plasma levels have been associated with the development of type II diabetes mellitus, an unhealthy body composition status, low physical fitness, and a higher risk of all-cause mortality." (PMID 31958773, 2020). "Finally, VitD can exert its beneficial effects via Klotho, one of its target genes that has been associated with longevity and whose protective effects against macrovascular complications of type 2 Diabetes were recently described." (PMID 32640692, 2020). "Studies in people with type 1 and type 2 diabetes have demonstrated that circulating Klotho levels are inversely associated with the degree of albuminuria and lower levels of Klotho can predict a faster decline of kidney function in people with type 2 diabetes." (PMID 39497615, 2025). "Recent investigations have illuminated the role of Klotho in the pathogenesis of type 2 diabetes and insulin resistance (IR)." (PMID 38907289, 2024). "In type 2 diabetes and its complications DN, a significant decrease in klotho expression has been observed." (PMID 37143722, 2023). "It has been reported that the decrease of plasma Klotho is closely related to the progression of DKD in patients with type 2 diabetes." (PMID 32908633, 2020). "In individuals with type 2 diabetes, the level of plasma soluble Klotho has been shown to correlate negatively with the development of albuminuria and with a decline in eGFR." (PMID 28194484, 2017). "Individuals with type 2 diabetes and an eGFR >60 ml/min have reduced tissue levels of Klotho compared with individuals with IgA nephropathy." (PMID 28194484, 2017). "Exogenous Klotho supplementation regulates glucose production by blocking the glucogenesis pathway and reversing insulin resistance in individuals with type 2 diabetes, averting fibrosis pathophysiology, pro-inflammatory indicators, and oxidative stress, and shielding the kidney from injury." (PMID 40119098, 2025). "Given that Klotho ameliorated abnormal lipid metabolism in the liver by upregulating PPARA expression in type 2 diabetic mice, our results suggest that Klotho may improve fatty acid oxidation by regulating PPARA and PPARGC1A expression." (PMID 38584258, 2024). "Klotho G395A polymorphism was significantly associated with a high risk of T2DM in both males and females, while C181T polymorphism was associated with the risk of type 2 diabetes in female subjects in the Pashtun population of Pakistan." (PMID 36140700, 2022). "Importantly, patients with type 2 diabetes have low soluble Klotho levels, and biopsies from patients with early stages of DN present diminished renal Klotho expression." (PMID 32046074, 2020). "The association, if any, between levels of soluble Klotho and CVD or renal endpoints in type 1 or type 2 diabetes is unknown." (PMID 28194484, 2017). "The following hypotheses were tested: 1) type 2 diabetes is associated with reduced sKlotho levels, particularly in patients with MVD and 2) hyperglycemia reduces renal Klotho expression." (PMID 23945089, 2013). "The common functional "KL-VS" variant in the KLOTHO (KL) gene is associated with longevity in humans but its role in type 2 diabetes is not known." (PMID 16753056, 2006). "Importantly, it was established that Klotho is involved in type 2 diabetes and insulin resistance." (PMID 37985893, 2023).